NOS1 (nitric oxide synthase 1)
Diseases named in the same sentence as NOS1 in open-access papers (continued):
Sharing a sentence is not in itself a finding about the gene and the disease.
nasopharyngeal carcinoma (4 papers, 2017 to 2024). A carcinoma arising from the nasopharyngeal epithelium. "We report that NOS1 reduces excessive levels of autophagy and promotes the survival of nasopharyngeal carcinoma (NPC) cells." (PMID 30952837, 2019). "Here we report that NOS1 reduces excessive levels of autophagy and promotes the survival of nasopharyngeal carcinoma cells." (PMID 28243469, 2017). "NOS1 can also activate the AKT/mTOR signaling pathway through the S-nitrosylation of PTEN, thereby inhibiting autophagy in nasopharyngeal carcinoma cells." (PMID 38877096, 2024).
neuropathic pain (4 papers, 2009 to 2012). Chronic pain caused by damage to nerve fibers. "In addition, CO located in neurons could also participates in the modulation of neuropathic pain by decreasing the production of NOS1 which would restrict the activation of microglia and attenuates the development of neuropathic pain." (PMID 22928017, 2012). "Our data showed that peripheral neuropathic pain increases the transcription and expression of NOS1 in the spinal cord of WT mice, indicating that NOS1 might be the main responsible for the maintenance of peripheral neuropathic pain after the total sciatic nerve ligation." (PMID 21179208, 2010).
prostate carcinoma (4 papers, 2014 to 2023). A carcinoma that arises from epithelial cells of the prostate gland. "NOS1 downregulation reduced the growth of chemokine expressing fibroblasts and their ability to promote tumor formation in prostate cancer cells." (PMID 33927218, 2021). "Concomitantly, over-expression of CXCL14 in fibroblasts stimulates tumor angiogenesis and growth of prostate cancer cells through activation of NOS1-derived nitric oxide signaling pathways." (PMID 25411967, 2014).
psychosis (4 papers, 2011 to 2021). "Since NO has an important role in regulating the release of neurotransmitters such as dopamine and serotonin, NOS1 is recognized to be a good candidate gene for disorder with psychosis." (PMID 21886582, 2011). "Based on previous evidences, we hypothesized that SNPs of NOS1 may play a role in ketamine-induced psychosis." (PMID 33424660, 2020). "Further studies are needed to investigate the role of NOS1 and NO in ketamine-related psychosis." (PMID 33424660, 2020). "Therefore, it would be of interest to examine the association between NOS1 and METH-induced psychosis." (PMID 21886582, 2011). "Therefore, we conducted a case-control association study between NOS1 and METH-induced psychosis with Japanese subjects (183 with METH-induced psychosis patients and 519 controls)." (PMID 21886582, 2011). "In conclusion, we suggest that NOS1 might not contribute to the risk of METH-induced psychosis in the Japanese population." (PMID 21886582, 2011). "In conclusion, our results suggest that NOS1 does not play a major role in METH use disorder with psychosis in the Japanese population." (PMID 21886582, 2011). "Since the ketamine model is one of the most common schizophrenic models, there is no study to test whether the genetic variation of NOS1 is involved in the occurrence of psychosis in some chronic ketamine users." (PMID 33424660, 2020).
attention deficit-hyperactivity disorder (3 papers, 2020 to 2026). A disorder characterized by a marked pattern of inattention and/or hyperactivity-impulsivity that is inconsistent with developmental level and clearly interferes with functioning in at least two settings (e.g. at home and at school). "Studies conducted in 2008 concluded that there is an association between neuronal nitric oxide synthase (nNOS1/NOS1) genes that generate nitric oxide (NO) and RLS and attention deficit hyperactivity disorder (ADHD) in children." (PMID 33083159, 2020).
cerebrovascular disease (3 papers, 2013 to 2022). "Thus, studies with large sample size, more haplotypes, and more examinations are required to functionally confirm the relationship between NOS1 gene and cerebrovascular disease in Han Chinese." (PMID 24082858, 2013).
diabetic nephropathy (3 papers, 2015 to 2024). "The logistic regression was used to assess the risk of developing diabetic nephropathy or the likelihood of renal replacement therapy based on NOS1, NOS2, and NOS3 polymorphisms." (PMID 39061907, 2024). "It was shown that the C/C genotype of the rs3782218 polymorphism in NOS1 is associated with a more than 12-fold increase in the odds of developing diabetic nephropathy (p = 0.035)." (PMID 39061907, 2024). "In summary, this study indicates the potential use of the rs3782218 polymorphism (NOS1) in assessing the risk of diabetic nephropathy or the likelihood of renal replacement therapy." (PMID 39061907, 2024). "Based on the logistic regression results, it was noticed that the rs3782218 polymorphism (NOS1) could potentially be used to predict the risk of developing diabetic nephropathy." (PMID 39061907, 2024). "The aim of this study was to assess the role of selected NOS polymorphisms—rs3782218 (NOS1), rs1137933 (NOS2), rs1799983, rs2070744, and rs61722009 (NOS3)—in the risk of developing diabetic nephropathy and in the likelihood of renal replacement therapy." (PMID 39061907, 2024). "Moreover, it was observed that the C genotype (rs3782218, NOS1) is associated with an increased likelihood of renal replacement therapy, which could confirm the previously obtained result related to the C/C genotype and the development of diabetic nephropathy." (PMID 39061907, 2024). "Lower NOS1 and NOS2 concentrations were observed in the diabetic nephropathy group compared to the control group (p = 0.002, p < 0.001, respectively)." (PMID 39061907, 2024).
glaucoma (3 papers, 2012 to 2020). Increased pressure in the eyeball due to obstruction of the outflow of aqueous humor. "Moreover, the genes NOS1 and PTGS2 have been associated with glaucoma." (PMID 23028713, 2012). "It was shown that NOS-2 is absent in healthy patients, while NOS-1 and NOS-3 are upregulated in glaucoma patients." (PMID 25914734, 2015).
pulmonary hypertension (3 papers, 2009 to 2023). Increased pressure within the pulmonary circulation due to lung or heart disorder. "NOS1 has been found to regulate pulmonary hypertension in animal models." (PMID 36964568, 2023).
adenoma (2 papers, 2013 to 2026). A neoplasm arising from the epithelium. "NOS1 hypermethylation was confirmed among CRCs in in-house dataset 1 (p < 0.001), and among CRCs and advanced adenomas in in-house dataset 2 (p < 0.001)." (PMID 42048609, 2026).
aortic stenosis (2 papers, 2020 to 2023). Aortic valve stenosis is a aortic valve disease caused by the incomplete opening of the aortic valve. "This increase in 3-NT in the aortic intima is consistent with the recent demonstration of increased nNOS/NOS1 in aortic stenosis formation in CD animals." (PMID 36834670, 2023).
autism spectrum disorder (2 papers, 2020 to 2024). A spectrum of developmental disorders that includes autism, and Asperger syndrome. "Unlike NOS2, the association study of NOS1 and NOS2 genes (see Section 2.3.2 “Autism Spectrum Disorders” regarding NOS2) with autism spectrum disorders (ASD) in an Asian population demonstrated no statistically significant results with respect toNOS1." (PMID 32111088, 2020).
brain tumor (2 papers, 2013 to 2020). "At first, 11 NOS1 SNVs demonstrated a statistically significant association (p ≤ 0.05) with one or more types of cerebral tumors or a significant modification of lead cumulative effects on brain tumors." (PMID 32111088, 2020).
diabetic cardiomyopathy (2 papers, 2012 to 2017). Diabetic cardiomyopathy is a disorder of the heart muscle in people with diabetes. "We previously showed that NOS1 was involved in altered β-adrenoceptor response in diabetic cardiomyopathy." (PMID 28727746, 2017). "Additionally, it has been proposed that in diabetic cardiomyopathy, there is an increase in nitric oxide synthase 1 (NOS1) with a disconnection in signaling between NOS1 and the sarcoplasmic calcium channel, the ryanodine receptor." (PMID 23251813, 2012).
lymphoma (2 papers, 2019 to 2023). A malignant (clonal) proliferation of B- lymphocytes or T- lymphocytes which involves the lymph nodes, bone marrow and/or extranodal sites. "The risk of lymphoma varies with dietary intake of fruits and vegetables in the presence of particular SNPs, such as NOS1, NOS2A, MPO, and SOD3, with more significant results for NOS1." (PMID 37759977, 2023). "Data obtained from this study showed that, especially in DLBCL and FL subtypes, the risk of lymphoma varies with dietary intake of fruits and vegetables in the presence of particular SNPs of some oxidative stress pathway genes, such as NOS1, NOS2A, MPO, and SOD3." (PMID 37759977, 2023).
male infertility (2 papers, 2014 to 2025). The inability of the male to effect fertilization of an ovum after a specified period of unprotected intercourse. "Thus, the aim of the present study was to investigate the associations between five polymorphisms in NOS genes (NOS1 rs2682826, NOS1 rs1047735, NOS2 rs2297518, and NOS2 rs10459953, and NOS3 rs1799983) and male infertility risk and also sperm DNA damage in a Chinese population." (PMID 25517965, 2014). "However, we did not found other four polymorphisms (NOS1 rs2682826, NOS1 rs1047735, NOS2 rs2297518, and NOS2 rs10459953) have any apparent relationship with risk of male infertility." (PMID 25517965, 2014).
neonatal encephalopathy (2 papers, 2017 to 2023). "Yu T found that nitric oxide synthase 1 (NOS1) gene was associated with spastic quadriplegia and CP with neonatal encephalopathy." (PMID 36323241, 2023).
pancreatic cancer (2 papers, 2017 to 2018). "HIPK3 has been related to apoptosis resistance, CBR1 has been identified as a patient survival marker, ALDH3A1 and ALDH3A2 have been related to drug response, and NOS1 has been related to pancreatic cancer risk." (PMID 29285214, 2017).
subarachnoid haemorrhage (2 papers, 2013 to 2020). "For instance, aminoguanidine inhibition of NOS2 activity ameliorates cerebral vasospasm after subarachnoid haemorrhage in rabbits via increase of NOS1 mRNA and protein levels." (PMID 23951240, 2013).
anxiety disorder (1 paper, 2024). A category of psychiatric disorders which are characterized by anxious feelings or fear often accompanied by physical symptoms associated with anxiety. "One potential genetic risk factor for anxiety disorders is the neuronal nitric oxide synthase gene (NOS1)." (PMID 39025836, 2024).
Bardet-Biedl syndrome (1 paper, 2017). A ciliopathy with multisystem involvement. "While the neuron-expressed Nitric oxide synthase 1 (Nos1) protein is well known for its role in neurotransmission, mutations in genes from the Bardet-Biedl syndrome (BBS) family, such as bbs4, result in an autosomal recessive disorder characterized by mental retardation and other severe symptoms." (PMID 28993314, 2017).
bone metastasis (1 paper, 2025). Transfer of a neoplasm from its primary site to bones. "Aldehyde dehydrogenase 2 family member (ALDH2) and nitric oxide synthase 1 (NOS1) have been linked to lymph node metastasis and bone metastasis in BRCA, respectively." (PMID 41278297, 2025).
brain stem tumor (1 paper, 2010). "Among the brain stem tumor patients there was an elevated number of NOS1 *276T minor allele carriers in both homo- and heterozygous forms, where p = 0.035, OR = 2.56, 95% confidence interval 1.10–5.96." (PMID 22649665, 2010).
bronchitis (1 paper, 2017). An acute or chronic inflammatory process affecting the bronchi. "Significant differences in the prevalence and risk of bronchitis were found in genotypes of LT-α and TNF-α, but not in ALOX5, LTC4S, TBXA2R, ADAM33, NOS1 and ORMDL3 in the Inuit populations residing both in Greenland and in Denmark." (PMID 28740106, 2017).
Encephalopathy (1 paper, 2017). Encephalopathy is a term that means brain disease, damage, or malfunction. "The results are reproducible, and more stringent criteria for encephalopathy yields improved prediction of NOS1 for NE." (PMID 28649562, 2017). "In our study, the levels of NOS1 were significantly higher in the umbilical cord blood of neonates with clinical encephalopathy than in normal controls." (PMID 28649562, 2017).
gastric outlet obstruction (1 paper, 2010). The hindering of output from the STOMACH into the SMALL INTESTINE. "nNOS) locus amongst them and a NOS1-knockout mouse showing a gastric outlet obstruction." (PMID 20300641, 2010).
gonadotroph adenomas (1 paper, 2013). "NOS1 and DAX1, regulated by and/or regulating the transcription factor SF-1, are highly expressed in human gonadotroph adenomas." (PMID 23756599, 2013).
holoprosencephaly (1 paper, 2016). Holoprosencephaly (HPE) is a complex brain malformation resulting from incomplete cleavage of the prosencephalon, occurring between the 18th and 28th day of gestation, and affecting both the forebrain and face, which results in neurological manifestations and facial anomalies of variable severity. "Interestingly, in cases of human holoprosencephaly (HPE) with severe ventral forebrain hypoplasia, it was reported that only subpopulations of cortical interneurons (namely, those which express either NOS1, NPY, or SST) were absent, while calretinin-positive interneurons were still detected." (PMID 27069486, 2016).
ischemic cardiomyopathy (1 paper, 2016). Ischemic cardiomyopathy is a cardiomyopathy in which a weakness in the muscle of the heart due to inadequate oxygen delivery to the myocardium with coronary artery disease being the most common cause. "The role of nitric oxide synthase 1 (NOS1) as a major modulator of cardiac function has been extensively studied in experimental models; however, its role in human ischemic cardiomyopathy (ICM) has never been analysed." (PMID 27041589, 2016).
lipodystrophy (1 paper, 2020). A congenital or acquired disorder characterized by abnormal loss or redistribution of the adipose tissue in the body. "PomceGFP was expressed in a distinct population to the protein seipin associated with lipodystrophy and the enzyme nitric oxide synthase 1 (nNOS)." (PMID 32166324, 2020).
metabolic myopathies (1 paper, 2008). "Since the skeletal muscle phenotype of KN1 mice is consistent with that of human metabolic myopathies, the NOS1 gene may be a novel candidate gene for this class of skeletal muscle disease." (PMID 18852886, 2008).
oncocytoma (1 paper, 2004). "NOS1 was expressed in tumour cells of oncocytomas, chromophobe RCC and in few cells of Fürhman I and II clear cell RCC." (PMID 15150612, 2004). "Our observation of a granular staining pattern with the antinitrotyrosine antibody, identical to that of NOS1, in tubular epithelial cells of normal renal parenchyma and in oncocytoma, is in line with this concept of ONOO− chemistry limited to close proximity of its source." (PMID 15150612, 2004).
panic disorder (1 paper, 2021). An anxiety disorder characterized by multiple unexpected panic attacks with persistent concern of recurring attacks. "We would like to thank Nanjing Brain Hospital, affiliated with Nanjing Medical University of China for their funding and support on this research of NOS1 methylation is associated with white matter microstructure in corpus callosum and greater panic disorder severity among PD patients submitted." (PMID 34733233, 2021). "NOS1 plays an essential role in neurite outgrowth and may thus affect the microstructure development of white matter (WM) in the corpus callosum (CC), which is known to be altered in panic disorder (PD)." (PMID 34733233, 2021).
restless legs syndrome (1 paper, 2020). A condition that occurs while resting or lying in bed; it is characterized by an irresistible urgency to move the legs to obtain relief from a strange and uncomfortable sensation in the legs. "The investigators suggested this might be due to general differences between certain samples, rather than the NOS1 association with restless legs syndrome (RLS)." (PMID 32111088, 2020).
sarcoma (1 paper, 2022). A usually aggressive malignant neoplasm of the soft tissue or bone. "In other previous studies, some genes (CCND1, CD109, NOS1, and ABLIM1) were found to be abnormally expressed in sarcomas, which can be used as prognostic markers or classification features for different sarcomas." (PMID 36619306, 2022).
skin cancer (1 paper, 2024). "A systematic review of gene–sun exposure interactions in skin cancer identified variants of MC1R, CAT, and NOS1 that could help explain the mechanism by which sun exposure causes CM." (PMID 39281383, 2024).
small intestinal disease (1 paper, 2021). "In our experiment, NSAID-induced small intestinal disease model rats intervened by berberine showed significantly change in HTR4, F2RL3, NPY, CRHR2, IL1b, VIP, AQP8, NOS1." (PMID 34284820, 2021).
spastic quadriplegia (1 paper, 2018). "The T allele of NOS1 SNP rs3782219 was negatively associated with spastic quadriplegia, and the genotype frequencies of rs10774909, rs37841475, and rs2682826 were significantly associated with CP + NE." (PMID 29940959, 2018). "The T allele of NOS1 SNP rs3782219 was negatively associated with spastic quadriplegia (OR = 0.742, 95% CI = 0.600–0.918, after SNPSpD correction, p = 0.023)." (PMID 29940959, 2018). "Both spastic tetraplegia and CP + NE are serious forms of CP, suggesting that NOS1 likely plays a more important role in the pathogenesis of severe CP." (PMID 29940959, 2018).
stomach diseases (1 paper, 2016). "Interestingly, though proteins such as Glyoxalase I (GLO1, DD = 3), Nitric Oxide Synthase (NOS1, DD = 3), Matrix metalloproteinase-9 (MMP9, DD = 2) and Acetylcholinesterase (ACHE, DD = 2) do not have high topological properties, they are all the therapeutic targets of stomach diseases." (PMID 27597117, 2016).